HCN4 (hyperpolarization activated cyclic nucleotide gated potassium channel 4)
Diseases named in the same sentence as HCN4 in open-access papers (continued):
Sharing a sentence is not in itself a finding about the gene and the disease.
Sinus bradycardia (continued). "We performed the detailed clinical investigation of the family and a deep in silico analysis of the discovered variants, showing the causal role of a new HCN4 variant in sinus bradycardia and its possible contribution to the phenotypic heterogeneity of LQTS type 3." (PMID 40299689, 2025). "First, we reviewed the scientific literature for publications on sinus bradycardia due to a loss-of-function mutation in HCN4, in which the clinical data on heart rate were preferably accompanied by in vitro data on the functional effects of the mutation of interest on the HCN4 current." (PMID 37760888, 2023). "In the present study, we tested whether the affected biophysical parameters of HCN4 variants can explain the severity of sinus bradycardia." (PMID 37760888, 2023). "Sinus bradycardia has been reported in relation to LQTS or HCN4 mutations." (PMID 36244448, 2022). "The results of other studies demonstrated that the cause of sinus bradycardia in patients with LVNC may be the presence of a pathogenic variant in the HCN4 gene." (PMID 35328031, 2022). "Importantly, familial sinus bradycardia linked to C-terminus truncation and loss of cAMP-dependent regulation of HCN4 was documented in 2010." (PMID 33868385, 2021). "This mutation, which is genetically linked to sinus bradycardia, reduces Ih density in neonatal rat ventricular myocytes by 80% and slows activation kinetics at physiologically relevant voltages with preferential effects on HCN4 channels compared to HCN248." (PMID 31235733, 2019). "Finally, HCN4 p.Met1113Val was another interesting candidate since HCN4 mutations contribute to familial sinus bradycardia with preliminary evidence for an association of HCN p.M1113V and post-partum sinus bradycardia." (PMID 27182706, 2016). "Mutations in HCN4 have been associated with the cardiac disease, sinus bradycardia (OMIM #163800)." (PMID 20886000, 2010). "These in silico experiments revealed a very strong correlation between the beating rate and Qf, suggesting that this (relatively) readily obtained Qf may prove a useful tool for risk stratification of sinus bradycardia due to loss-of-function mutations in HCN4." (PMID 37760888, 2023). "We have previously shown that a downregulation of the key pacemaking ion channel, HCN4 (hyperpolarization-activated cyclic nucleotide gated channel 4), and the corresponding ionic current (funny current or If) in the sinus node underlies the sinus bradycardia in rodent models of exercise training." (PMID 28821541, 2017). "In 2003, an HCN4 variant (573X) causing truncation of HCN4 C-terminus was first identified in a patient with SND, presented as sinus bradycardia and chronotropic incompetence." (PMID 33868385, 2021). "In vivo, intraperitoneal injection of an antimiR to miR-370-3p into heart failure mice silences miR-370-3p and restores HCN4 mRNA and protein and If in the sinus node and blunts the sinus bradycardia." (PMID 32647133, 2020). "We show that in a mouse model of heart failure there is an upregulation of miR-370-3p in the sinus node (but not in ventricular muscle) and this results in a downregulation of HCN4 and If and consequently sinus bradycardia." (PMID 32647133, 2020). "Our previous work in rodent models has shown training-induced sinus bradycardia to be due to microRNA (miR)-mediated transcriptional remodeling of the HCN4 channel, leading to a reduction of the “funny” (If) current in the sinoatrial node (SAN)." (PMID 33551824, 2020). "Familial forms of primary sinus bradycardia have been attributed to alterations in HCN4." (PMID 35328031, 2022). "Here we show that, in a mouse model of heart failure in which there is sinus bradycardia, there is upregulation of a microRNA (miR-370-3p), downregulation of the pacemaker ion channel, HCN4, and downregulation of the corresponding ionic current, If, in the sinus node." (PMID 32647133, 2020).
Sinus bradycardia (continued). "Targeting miR-423-5p reversed exercise training-induced hyperpolarization-activated cyclic nucleotide-gated potassium channel 4 (HCN4) remodeling and sinus bradycardia." (PMID 34955881, 2021). "Up to 35% of healthy individuals below 25 years of age, trained athletes, and those with a rare form of the familial syndrome with potassium/sodium hyperpolarization-activated cyclic nucleotide-gated channel 4 (HCN4) mutation may have asymptomatic sinus bradycardia without any heart diseases." (PMID 32818118, 2020). "Among the three patients with sinus bradycardia (P29 through P31), two siblings (P30 and P31) with sick sinus syndrome demonstrated LVNC with dilatation of the ascending aorta, as did patients P2–P5, with HCN4 alterations." (PMID 35893073, 2022). "Here, we identified a novel heterozygous mutation HCN4-R666Q, which was located in the non-cAMP-binding region of CNBD, in two sporadic patients with sinus bradycardia, QT prolongation, and short bursts of ventricular tachycardia." (PMID 36244448, 2022).
sick sinus syndrome (20 papers, 2015 to 2025). A constellation of signs and symptoms which may include syncope, fatigue, dizziness, and alternating periods of bradycardia and atrial tachycardia, which is caused by sinoatrial node dysfunction. "Previous reports mainly focused on the association between HCN4 gene mutations and sick sinus syndrome (SSS)." (PMID 40613349, 2025). "Mutations in HCN4 have been associated with sick sinus syndrome and early-onset atrial fibrillation." (PMID 33497365, 2021). "In zebrafish, it has been shown that morpholino-based knockdown of hcn4 causes bradycardia and sinus pauses reminiscent of the sick sinus syndrome phenotypes found in patients with HCN4 mutations." (PMID 33572147, 2021). "Here, we sought to characterize a HCN4 V759I variant detected in a patient with a family history of sick sinus syndrome." (PMID 33095298, 2020). "The genomic analysis yielded a mono-allelic HCN4 V759I variant in a 49-year-old woman presenting with a family history of sick sinus syndrome." (PMID 33095298, 2020). "HCN4 channel abnormality may cause bradycardia and sick sinus syndrome, making it an important target for clinical research and drug discovery." (PMID 35846012, 2022). "Mutations in HCN4 are associated with sick sinus syndrome in humans." (PMID 33572147, 2021). "HCN4 pacemaker channels are the well‐known causative molecule of congenital sick sinus syndrome." (PMID 29315578, 2018). "A novel HCN4 mutation (c.2036 G>A) may lead to sick sinus syndrome." (PMID 40613349, 2025). "Furthermore, the HCN4 channel is mainly expressed in the heart, and mutations in the HCN4 gene may cause sick sinus syndrome and other cardiac disorders." (PMID 35846012, 2022). "We previously reported a mutation of HCN4 found in a patient suffering from sick sinus syndrome (SSS)." (PMID 26384234, 2015). "The mice also displayed reduced expression of HCN4 in SANCs and typical electrophysiological signs of sick sinus syndrome." (PMID 35872997, 2022). "LVNC induced by HCN4 and EMD mutations complicated sick sinus syndrome (SSS), AF, atrial standstill, and interventricular block." (PMID 34819141, 2021). "A large number of studies have shown that the HCN4 gene and its pacemaker current are closely related to sick sinus syndrome." (PMID 29899698, 2018). "In sick sinus syndrome, mitochondrial oxidative stress was found to induce HCN4 downregulation." (PMID 35872997, 2022). "So far, such risk stratification has been applied to SCN5A, KCNQ1, and KCNH2 gene variants associated with Brugada syndrome and long QT syndrome types 1 and 2, respectively, but risk stratification of HCN4 gene variants related to sick sinus syndrome has not yet been performed." (PMID 37760888, 2023). "The present study attempts to investigate the effect of astragaloside on the HCN4 gene and pacemaker current (If) in SAN cells of neonatal rabbits and directly reveal the electrophysiological mechanisms of astragaloside in the treatment of bradyarrhythmia and sick sinus syndrome." (PMID 29899698, 2018).
atrial fibrillation (14 papers, 2013 to 2023). A disorder characterized by an electrocardiographic finding of a supraventricular arrhythmia characterized by the replacement of consistent P waves by rapid oscillations or fibrillatory waves that vary in size, shape and timing and are accompanied by an irregular ventricular response. "In the genetic model of ivabradine, the competing risk analysis accounting for atrial fibrillation showed that the HCN4 heart rate-reducing variant protected against heart failure (HR = 0.90, 95% CI: 0.83–0.98, P = 0.013)." (PMID 32692755, 2020). "The results from the marginal models and the competing risk analyses do suggest opposing effects of the heart rate-reducing HCN4 variant on atrial fibrillation and heart failure." (PMID 32692755, 2020). "We tested the association between the heart rate reducing allele of the HCN4 variant rs8038766 and atrial fibrillation and stroke, a common and well-known consequence of atrial fibrillation." (PMID 32692755, 2020). "HCN4 has previously been implicated in atrial fibrillation, and we replicated these results using rs8038766." (PMID 32692755, 2020). "Genetically predicted heart rate reduction from the HCN4 gene variant rs8038766 was associated with an increase in risk of atrial fibrillation, recapitulating the observations from the SIGNIFY and SHIFT trials." (PMID 32692755, 2020). "Less obviously, the HCN4 locus had already been identified as a susceptibility locus for atrial fibrillation (AF) in another GWAS." (PMID 25642760, 2015). "Expression levels of HCN2 and HCN4 increased with age, and a greater increase was identified in patients with age-associated atrial fibrillation compared with that in those with aged sinus rhythm." (PMID 26005035, 2015). "Interestingly, KCNQ1:c.1394-39T>G and HCN4:c.1979-41A>G variants were found linked with atrial fibrillation in the patient and the fulfillment of depolarization abnormalities diagnostic criteria, respectively." (PMID 36008935, 2022). "It was therefore suggested that this age-associated increase in HCN2 and HCN4 expression enhanced the If current and therefore may increase the incidence of ventricular premature beats and atrial tachycardia, triggering atrial fibrillation." (PMID 26005035, 2015). "This may be explained partly by the inaccuracy of extrapolation of the OR estimate derived from a single genetic variant, and also possibly by an effect of HCN4 on atrial fibrillation that may be specific to modulation of the If current or other structural consequences of HCN4 variants." (PMID 32692755, 2020). "It was hypothesized that age-dependent changes in HCN2, HCN4, miR-1 and miR-133 expression may contribute to age-associated atrial fibrillation, and therefore the correlation between expression levels, among adult (≤65 years) and aged patients (≥65 years), and sinus rhythm was determined." (PMID 26005035, 2015). "HCN4, the target of the antiarrhythmic drug dronedarone, was prioritized as a disease gene for atrial fibrillation only through the GWAS method." (PMID 37492104, 2023). "These two highly significant SNPs (rs10842383 near LINC00477, P=3.45 × 10−7 and rs2680344 in HCN4, P=4.34 × 10−7 had large opposite effects on atrial fibrillation, while both decreased HRV." (PMID 28613276, 2017). "Compared with aged patients with sinus rhythm, aged patients with atrial fibrillation exhibited significantly higher HCN2 and HCN4 channel mRNA and protein expression levels (P<0.05), but significantly lower expression levels of miR-1 and miR-133 (P<0.05)." (PMID 26005035, 2015). "In patients with aged atrial fibrillation, the expression of HCN2 and HCN4 channels was enhanced compared with aged and adult sinoatrial fibrillation patients, whereas expression levels of miR-1 and miR-133 were lower." (PMID 26005035, 2015).
atrial fibrillation (continued). "Compared with the aged sinus rhythm group, the aged atrial fibrillation group also exhibited significantly enhanced levels of HCN2 and HCN4 mRNA expression (P<0.05; HCN2, 1.00±0.08 vs. 0.49±0.07; HCN4, 1.05±0.23 vs. 0.53±0.09)." (PMID 26005035, 2015). "Similarly, the aged atrial fibrillation group exhibited significantly enhanced HCN2 and HCN4 protein expression levels compared to those of the aged sinus rhythm group (P<0.05; HCN2, 1.04±0.19 vs. 0.92±0.12; HCN4, 1.12±0.11 vs. 1.02±0.08)." (PMID 26005035, 2015). "However, the upregulation of Hcn4 in the left atria, particularly in the context of Kir2.1 downregulation, could also potentially contribute to the ectopic atrial activity observed in the atrial AMPK-dKO mice prior to the development of atrial fibrillation." (PMID 35451373, 2022).
heart failure (14 papers, 2015 to 2025). Inability of the heart to pump blood at an adequate rate to meet tissue metabolic requirements. "Bradyarrhythmias are an important cause of mortality in heart failure and previous studies indicate a mechanistic role for electrical remodelling of the key pacemaking ion channel HCN4 in this process." (PMID 32647133, 2020). "Furthermore, miR-147 targets and inhibits hyperpolarisation-activated cyclic nucleotide-gated potassium channel 4 (HCN4) gene expression, which when upregulated, is supposed to be responsible for causing heart failure and ischemic cardiomyopathy." (PMID 38256030, 2024). "Heart failure was associated with a 9-fold upregulation of HCN4 in the ventricular septum." (PMID 26509807, 2015). "Thus, ivabradine treatment should be administered with caution, while HCN4 overexpression may be an indicator of heart failure and/or sudden death risk." (PMID 34835334, 2021). "In the sinus node in heart failure, silencing of miR-370-3p by antimiR-370-3p blunted or reversed the downregulation of HCN4 mRNA and protein and the density of If; antimiR-370-3p also blunted the bradycardia in vivo." (PMID 32647133, 2020). "Sinus node cells were isolated from control and heart failure mice and immunolabelled for HCN4 protein and image analysis showed a statistically significant decrease in HCN4 protein immunolabelling in the heart failure mice." (PMID 32647133, 2020). "For example, HCN2 and HCN4 channels are upregulated in heart failure, giving rise to potentially lethal arrhythmias." (PMID 32948209, 2020). "Here the authors generate HCN4 transgenic mice and show that upregulation of funny current to the levels observed in human heart failure alters calcium homeostasis leading to cardiac remodelling and arrhythmia." (PMID 31337768, 2019). "We generated transgenic mice (HCN4tg/wt) to assess functional consequences of HCN4 overexpression-mediated If increase in cardiomyocytes to levels observed in human heart failure." (PMID 31337768, 2019). "Also, experimental inflammatory response was suggested to downregulate HCN4 and impair sinus node pacemaking in a mouse model of heart failure." (PMID 39596280, 2024). "These miRNAs also target the glutathione transferase P1 (GSTP1), an enzyme involved in detoxification and a potential biomarker of myocardial stress and heart failure, and the hyperpolarization-activated cyclic nucleotide-gated 4 (HCN4) channel, a transmembrane protein which regulates heart rate." (PMID 39684483, 2024). "Ivabradine downregulates HCN4 expression in animal models of heart failure." (PMID 36769115, 2023). "In this group, there were 3,385 incident heart failure cases and the HCN4 variant rs8038766 showed a non-significant trend for a protective effect (HR = 0.96, 95% CI: 0.89–1.02; P = 0.177)." (PMID 32692755, 2020). "In summary, we have identified five factors that could be involved in the downregulation of HCN4 in the sinus node in heart failure: Isl1, NRSF, Tbx18, miR-139-3p and miR-370-3p." (PMID 32647133, 2020). "What is responsible for the remodelling of the sinus node, in particular of HCN4, in heart failure?" (PMID 32647133, 2020). "HCN4 is a direct transcriptional target of AP1 and Mef2c39, but these transcription factors were significantly upregulated in the sinus node in heart failure and cannot explain the downregulation of HCN4." (PMID 32647133, 2020). "HCN1 showed an overall significant downregulation in heart failure animals (2-way ANOVA, P = 0.001), while HCN4 was upregulated in the left ventricular septum (Limma test, P = 003)." (PMID 26509807, 2015). "However, NRSF is potentially involved: NRSF was significantly upregulated in the sinus node in heart failure; NRSF is a transcriptional repressor and binds to a silencer element within an intron of HCN4 and prevents its transcription." (PMID 32647133, 2020).
heart failure (continued). "Of the transcription factors known or predicted to regulate HCN4 (AP1, Isl1, Mef2c, Nkx2.5, NRSF, Tbx3 and Tbx18), two (Nkx2.5 and Tbx3) did not change in the sinus node in heart failure." (PMID 32647133, 2020).